ERAP1 (endoplasmic reticulum aminopeptidase 1)
Diseases named in the same sentence as ERAP1 in open-access papers (continued):
Sharing a sentence is not in itself a finding about the gene and the disease.
congenital toxoplasmosis (1 paper, 2020). Toxoplasma infection that is present from birth. "Polymorphisms in the human endoplasmic reticulum-associated aminopeptidase (ERAAP) gene ERAP1 were associated with susceptibility to human congenital toxoplasmosis, emphasis the importance of MHC Class I antigen processing in humans in response to T. gondii." (PMID 33324583, 2020).
familial Mediterranean fever (1 paper, 2018). Familial Mediterranean fever (FMF) is an autoinflammatory disorder characterized by recurrent short episodes of fever and serositis resulting in pain in the abdomen, chest, joints and muscles. "ERAP1 SNPs have also been investigated in Familial Mediterranean fever (FMF), an autosomal recessive autoinflammatory disorder resulting in fever, skin rash and inflammation of the peritoneum." (PMID 30054427, 2018).
hantavirus infections (1 paper, 2025). "We further evaluated the association of ten most common ERAP1 haplotypes on severe PUUV infection and tested their association with hantavirus infections." (PMID 39533856, 2025).
hepatocellular carcinoma (1 paper, 2023). A malignant tumor that arises from hepatocytes. "In hepatocellular carcinoma cells (HCC), NK cells tolerate ERAP-deficient HCCs and the prompt killing of ERAP1-expressing HCCs." (PMID 36834865, 2023).
Infertility (1 paper, 2021). "Women carrying the rs26653 ERAP1 GG/HLA-C2C2 combination were protected from infertility and RIF, while those with GC/HLA-C2C2 were predisposed." (PMID 34745129, 2021). "Carriers of ERAP1 rs6861666 AA and KIR in the BB centromeric region are at risk of infertility and RIF (p/pcorr. = 0.001/0.010, OR = 7.435, and p/pcorr. = 0.003/0.029, OR = 12.373, respectively)." (PMID 34745129, 2021). "The rs2287987 ERAP1 CT/KIR Tel BB combination protects against infertility and RIF (p/pcorr. = 0.001/0.007, OR = 0.111, and p/pcorr. = 0.002/0.016, OR = 0.055, respectively)." (PMID 34745129, 2021). "In turn, the rs2287987 ERAP1 CT/KIR Tel BB combination protects against infertility and RIF." (PMID 34745129, 2021). "Women carrying rs26653 ERAP1 GG/HLA-C2C2 combination are protected from infertility and RIF (p/pcorr. = 0.002/0.022, OR = 0.343, and p/pcorr. = 0.001/0.005, OR = 0.252, respectively), while those with CG/HLA-C2C2 are predisposed to RIF (p/pcorr. = 0.002/0.016, OR = 3.661)." (PMID 34745129, 2021). "However, they did not detect any associations with PE for rs27044, rs26653, and rs26618 of ERAP1 and rs2248374 of ERAP2 as we did for RIF and infertility." (PMID 34745129, 2021). "Carriers of the genotype ERAP1 rs6861666 AA and KIR Cen BB are predisposed to infertility and RIF." (PMID 34745129, 2021). "The protection against infertility and RIF is also observed in women with GG ERAP1 rs26653/HLA-C2C2/KIR AA combination (p/pcorr. = 0.003/0.025, OR = 0.093, and p/pcorr. = 0.004/0.036, OR = 0.084, respectively)." (PMID 34745129, 2021).
intestinal inflammation (1 paper, 2022). "Together, these results suggest that ERAP1 deficiency also results in exaggerated colonic cytokine and chemokine responses during inflammasome (DSS)-induced intestinal inflammation." (PMID 35246034, 2022). "We investigated the impact that ERAP1 functions have on inflammasome and TLR receptor regulation ex vivo using a BMDM-based model for analyzing inflammasome and ER stress responses, and in vivo by utilizing the DSS-induced intestinal inflammation model." (PMID 35246034, 2022).
Juvenile onset (1 paper, 2011). Onset of signs or symptoms of disease between the age of 5 and 15 years. "We present evidence for subtype specific association of the IL23R gene with juvenile-onset PsA and ERAP1 gene with the ERA subtype of JIA." (PMID 21281511, 2011).
lymph node metastases (1 paper, 2023). "In contrast, an increased risk of tumor progression and lymph node metastases in Dutch populations is significantly associated with ERAP1-coding SNPs." (PMID 36834865, 2023).
malaria (1 paper, 2019). Malaria is a serious and sometimes fatal disease caused by a parasite that commonly infects a certain type of mosquito which feeds on humans. "Based on our recent findings, in this perspective article we speculate that the Endoplasmic Reticulum Amino Peptidases, ERAP1 and 2, associated with AS and involved in antigen presentation, underwent co-selection by malaria." (PMID 30740100, 2019). "In conclusion, functional variants of the three aminopeptidases ERAP1, ERAP2, and LNPEP show a worldwide distribution compatible with a selective pressure by malaria." (PMID 30740100, 2019).
Mediterranean fever (1 paper, 2021). "The revolution of the genome-wide association study (GWAS) era has identified hundreds of genes associated with SpA, mainly IL23R, ERAP1 (Endoplasmic Reticulum Aminopeptidase-1), ERAP2, and MEFV (Mediterranean fever) linked to innate and acquired immune response and cytokines production." (PMID 34447407, 2021).
metabolic syndrome (1 paper, 2024). A cluster of metabolic risk factors for CARDIOVASCULAR DISEASES and TYPE 2 DIABETES MELLITUS. "The remaining ten drugged proteins were targeted by compounds indicated for treatment of cancers (CAN2, EPHB1, ERAP1, GSTM3, NQO1, and PVRL4), mitochondrial and muscular disease (NQO1), and metabolic syndrome (CEL)." (PMID 39434187, 2024).
Miscarriage (1 paper, 2021). A pregnancy that ends at a stage in which the fetus is incapable of surviving on its own, defined as the spontaneous loss of a fetus before the 22th week of pregnancy. "rs30187 of ERAP1 seems to play a role in susceptibility to recurrent miscarriage after natural fertilization." (PMID 34745129, 2021).
pancreatic cancer (1 paper, 2022). "A study of the liver metastasis of pancreatic cancer cells suggested that endoplasmic reticulum aminopeptidase 1 (ERAP1)-secreting exosomes enhance the phagocytic capacity and NO synthesis activity of macrophages." (PMID 36311698, 2022).
psoriasis vulgaris (1 paper, 2024). Plaque psoriasis is the most common presentation of psoriasis. "ERAP1 gene mutation may be associated with psoriasis vulgaris and HLA‐C0602 in Han nationality in Inner Mongolia." (PMID 39570751, 2024). "This study aimed to investigate the association between genetic variants of ERAP1 (OMIM: 606832) and psoriasis vulgaris (PsV) susceptibility in Inner Mongolia Han nationality." (PMID 39570751, 2024).
renal cell carcinoma (1 paper, 2014). "In renal cell carcinomas, ERAP1 and ERAP2 appear to have a different behavior, being the first more frequently up-regulated and the latter more frequently down-regulated, as compared to the normal counterpart." (PMID 25566501, 2014). "In another study, expression of ERAP1 and ERAP2 was investigated in 300 normal kidney tissues and 334 renal cell carcinoma lesions." (PMID 25566501, 2014).
cancer (48 papers, 2012 to 2025). A tumor composed of atypical neoplastic, often pleomorphic cells that invade other tissues. "ERAP1 polymorphisms are associated with variable function and susceptibility to cancer, autoimmune disorders and infectious diseases, and its expression can be altered under pathological conditions." (PMID 40265075, 2025). "Higher ERAP1 values (targeted by tosedostat) were shown to be associated with lower plasma PC values and HF risk, is targeted by cancer drug tosedostat, and plays a role in blood pressure regulation." (PMID 39434187, 2024). "ERAP1 expression supports tumor progression, but differences in the ERAP1 association with cancer exist among different ethnic groups." (PMID 36834865, 2023). "As ERAP1 inhibitors are increasingly being considered as potential therapeutics for cancer immunotherapy and autoimmunity, the effect of common ERAP1 polymorphisms on inhibitor potency must be considered." (PMID 34489420, 2021). "ERAP1 is polymorphic and several common allotypes exist in the population affecting its functional properties and predisposition to disease such as cancer and autoimmunity." (PMID 34389743, 2021). "The downregulation of ß2-m,TAP1, TAP2, LMP7, ERAP1, tapasin, and ERp57 protein expression positively associated with HLA-I expression in CIN lesions, whereas ß2-m, TAP1, TAP2, LMP2, LMP7, ERAP1, ERp57, and tapasin expression positively associated with HLA-I in the cancerous lesions." (PMID 23024775, 2012). "Therefore, rs30187 in ERAP1 was found here to be associated both with risk of cancer and survival." (PMID 34149699, 2021). "Thus, ERAP1 polymorphisms may work differently in response to different cancers most likely associated with different HLA alleles and therefore requiring different preparation of antigenic peptides for efficient immune response." (PMID 34149699, 2021). "Here, we combined immunopeptidomics with proteomic, biochemical, and metabolic analyses to better understand the effect of ERAP1 activity on cancer cells." (PMID 40189142, 2025). "A comparable effect was also reproduced to a reasonable extent in another cancer cell line carrying a different combination of ERAP1 haplotypes." (PMID 40189142, 2025). "Polymorphisms in the ERAP1 and ERAP2 genes have been associated with a range of cancers, as well, suggesting their involvement in tumor development and progression." (PMID 40226591, 2025). "This dominant-negative impact results in reduced angiogenesis and has been shown to halt tumor growth, providing significant evidence for ERAP1’s role in cancer cell cycle regulation." (PMID 40226591, 2025). "This is all the more relevant as ERAP1 inhibitors become increasingly relevant compounds of interest for cancer therapy research and development." (PMID 40113210, 2025). "The polymorphisms of the ERAP1 and ERAP2 genes play an important role in oncological pathology, and their expression is frequently modified in various forms of cancer, including lung, colon, prostate, kidney, bladder, cutaneous, and hematological cancers." (PMID 38534723, 2024). "ERAP1 inhibition results in the greater activation of T and NK cells and a substantial change in the peptides present on the cancer cell surface to immune effector cells." (PMID 36834865, 2023). "As an important component of the antigen processing and presenting machinery – APM, ERAP1 is frequently down-regulated in many cancers." (PMID 37101107, 2023). "As demonstrated here, ERAP1 and ERAP2 are associated with irregular peptides in the HLA system, several pregnancy complications, and cancers." (PMID 36834865, 2023). "A comparison of the similarities and differences between pregnancy and cancer and the roles ERAP1 and ERAP2 play in their progression is analyzed further." (PMID 36834865, 2023). "In cancer and autoimmune disorders, ERAP1 and ERAP2 are emerging molecules and double-edged swords regarding immune responses." (PMID 36834865, 2023).
cancer (continued). "ERAP2 expression in cancer tends to be opposite to ERAP1, as ERAP2 deficiency is correlated with cancer growth through immune evasion." (PMID 36834865, 2023). "ERAP1 is among the most conserved genes in WT cancers (SR = -2.797) and ERAP2 among the most conserved in mKRAS (SR = -2.085)." (PMID 36092893, 2022). "Multiple associations of ERAP1 genetic variants, not only with NSCLC risk but also with disease course and response to treatment, described here, support the thesis that ERAP1 aminopeptidase can take part in the anti-cancer immune response." (PMID 34149699, 2021). "ERAP1 knockout in mouse syngeneic cancer models has resulted in tumor rejection and significantly improved survival." (PMID 33887439, 2021). "In some cancers, ERAP1 overexpression leads to destruction of tumor-specific immunodominant epitopes and induction of anti-tumor CD8+ responses, linking antigen destruction with tumor escape." (PMID 33406696, 2021). "Other factors influencing OS were: stage of cancer, gender, and, unexpectedly, the ERAP1 rs30187 genotype." (PMID 34149699, 2021). "In other cases, ERAP1 downregulation can lead to cancer rejection through Natural Killer cell mediated cytotoxicity." (PMID 33406696, 2021). "As part of a recent study into the role of ERAP1 in cancer, we now report our investigation into the use of 1 as tool compound to study ERAP1 inhibition." (PMID 33887439, 2021). "Due to its important role in adaptive immune responses, ERAP1 is an emerging target for cancer immunotherapy and inflammatory diseases with autoimmune etiology." (PMID 34389743, 2021). "Cancers with EP300/CBP loss of function (LOF; deletion and/or copy number variants [CNV] loss) showed lower ERAP1 and IFNGR1 or HLA-A expression." (PMID 33602823, 2021). "Our findings unveil an unexpected role for ERAP1 in cancer and indicate ERAP1 as a promising therapeutic target for Hh-driven tumors." (PMID 31341163, 2019). "As partial or complete LOH has been shown to be an important factor in various human carcinomas, the role of allelic instability in ERAP1 downregulation was assessed." (PMID 26146606, 2015). "In one study, the genetic down-regulation of ERAP1 in cancer cells that establish solid tumors in mice resulted potent NK cell-mediated cytotoxic responses." (PMID 25566501, 2014). "A recently developed potent ERAP1/ERAP2 inhibitor was successfully used to induce CTL responses against the cancer cells used in that study." (PMID 25566501, 2014). "•ERAP1 silencing or chemical inhibition can also affect the proteome of cancer cells." (PMID 40189142, 2025). "Given the surprisingly large effect of both genetic and pharmacological inhibition of ERAP1 on the proteome of A375 cells, we inquired whether this phenomenon is specific to A375 cells or is more general to other cancer cells." (PMID 40189142, 2025). "Modulation of ERAP1 activity can generate unique immunopeptidomes in cancer cells, mainly due to altered peptide processing in the ER, but also induce changes in the cellular proteome and metabolic state which may have further effects on tumor cells." (PMID 40189142, 2025). "By promoting or inhibiting these processes depending on the cellular context, ERAP1 could serve as a key regulator in the balance between normal tissue repair and pathological angiogenesis seen in conditions like cancer." (PMID 40226591, 2025). "Interestingly, ERAP1 expression varies in different cancers—it can be increased or decreased (the most common situation), but complete loss of expression is not common." (PMID 37101107, 2023). "We did not detect any association between mRNA ERAP1 expression level in normal tissue and: (i) age at diagnosis (p = 0.8386), (ii) patient’s sex (p = 0.3616), (iii) histological type of cancer (p = 0.7580) and (iv) clinical stage of NSCLC (p = 0.7549)." (PMID 37101107, 2023).
cancer (continued). "Similar to many other genes, ERAP1 expression can be down-regulated in cancer cells by different mechanisms, including epigenetics (DNA methylation, histone post-translational modification), transcriptional and translational regulation, as well as post-translational modifications." (PMID 37101107, 2023). "In lung tumor tissue, the effect of rs26653 (or another SNP being in strong LD with it) on ERAP1 expression may be masked by other mechanisms regulating expression, characteristic of this cancer type." (PMID 37101107, 2023). "Other tested polymorphisms did not correlate with ERAP1 mRNA levels either in cancer or in normal tissue." (PMID 37101107, 2023). "If CC homozygotic patients suffering from NSCLC survived longer, we may suppose that less active ERAP1 favored generation of much more immunogenic cancer epitopes recognized by the immune system." (PMID 34149699, 2021). "Both ERAP1 and ERAP2 have been shown to be downregulated in some cancers, play key roles in the shaping of the cellular immunopeptidome, and their activity has been associated with changes in anti-cancer immune responses." (PMID 33406696, 2021). "In this study we demonstrated that all tested ERAP1 single nucleotide polymorphisms, except rs26618, conferred susceptibility to cancer not only in never-smokers, but also in smokers, although in the opposite direction." (PMID 34149699, 2021). "Taken together, our results suggest that inhibition of ERAP1 function may have important therapeutic applications in NK cell-based cancer immunotherapy." (PMID 34917091, 2021). "In never-smokers, with the same ERAP1 haplotype, other proteins are expressed being potential source of epitopes leading to the recognition and killing of cancer cells by T cells, but this particular ERAP1 variant does not produce suitable epitopes from them." (PMID 34149699, 2021). "In conclusion, our study reveals an unexpected function of ERAP1 in cancer development suggesting that targeting ERAP1 could open innovative perspectives for effective therapeutic approaches in the treatment of Hh-dependent tumors." (PMID 31341163, 2019). "Herein, we uncovered an unexpected role of ERAP1 in regulating Hh-dependent tumorigenesis, thus providing further evidence that inhibition of ERAP1 may be exploited for cancer treatment." (PMID 31341163, 2019). "These encouraging results, in the context of cancer, have shown that reducing ERAP1/ERAP2 activity can alter the immune response, which may well prove protective in AS and BSCR." (PMID 30054427, 2018). "Since ERAP1 is a target molecule for cancer immunotherapy, it may be worth exploring whether its secondary effects on the proteome and metabolism of cancer may be exploited pharmacologically to synergize with the effects on adaptive immunity to enhance antitumor therapies." (PMID 40189142, 2025). "Besides peroxisomal respiration, diminishment of ROS can also occur indirectly as a result of increased glycolysis in cancer cells, also known as the Warburg effect, due to diversion of substrates from the electron transport chain, which we also observed in the ERAP1 KO cells." (PMID 40189142, 2025). "The objective was to find ERAP1 inhibitors,using physiologically relevant antigenic peptide substrates, workingtoward the “overtrimming” hypothesis, where it is thoughtthat ERAP1 may destroy mature antigenic peptides of cancer cells." (PMID 39691536, 2024). "Thus, we suggest that in the heterozygotes both allotypes of ERAP1 could in total utilize a broader spectrum of substrates and the chance of generation of more immunogenic cancer epitope(s) is much greater than in the case of homozygotes." (PMID 34149699, 2021). "Alternatively, high-activity ERAP1 present in patients with TT and, at lower level, with CT genotypes might destroy (by over-trimming) some cancer epitopes, and therefore the efficient cancer elimination by immune cells was impaired." (PMID 34149699, 2021).